IL15 (interleukin 15)
Diseases named in the same sentence as IL15 in open-access papers (continued):
Sharing a sentence is not in itself a finding about the gene and the disease.
small cell lung carcinoma (1 paper, 2017). Small cell lung cancer (SCLC) is a highly aggressive malignant neoplasm, accounting for 10-15% of lung cancer cases, characterized byrapid growth, and early metastasis. "In an earlier study, we observed that transfection with genes encoding different IL-15 variants genes led to obvious decreases in the proliferation of NCI-H446 small cell lung cancer cells." (PMID 29296227, 2017). "In the present study, we assessed the effects of transfecting NCI-H446 small cell lung cancer cells with genes encoding three IL-15 variants: prototypical IL-15, mature IL-15 peptide, and modified IL-15 in which the IL-2 signal peptide is substituted for the native signal peptide." (PMID 29296227, 2017). "In sum, our findings suggest IL-15 suppresses NCI-H446 small cell lung cancer cell proliferation through cell cycle arrest mediated by cyclin E and CDK2." (PMID 29296227, 2017). "Consistent with that idea, we found that modifying IL-15 with the IL-2 signal peptide enhanced IL-15 secretion as well as its ability to induce cell cycle arrest in NCI-H446 small cell lung cancer cells and increase NK cell antitumor activity." (PMID 29296227, 2017). "Thus IL-15 appears to effectively reduce the tumorigenicity of NCI-H466 small cell lung cancer cells." (PMID 29296227, 2017).
squamous cell carcinoma (1 paper, 2022). A carcinoma arising from squamous epithelial cells. "Administration of Cetuximab and IL-15 superagonist N-803 (formerly ALT-803) in mice harboring Cal27 squamous cell carcinoma of head and neck tumors significantly decreased tumor volume when compared to controls and single-agents treatment alone." (PMID 36300122, 2022).
Ss (1 paper, 2018). "We hypothesized that Ss infection would be associated with alterations in memory T cell subset distribution, alterations that could be reflective of changes in IL-2, IL-4, IL-7, IL-9 and IL-15." (PMID 29795573, 2018).
synovitis (1 paper, 2005). Inflammation of a synovial membrane. "Early RA synovial fluid was characterized by significantly elevated levels of T cell related cytokines (IL-2, IL-4, IL-13 and IL-17) and stromal cell and macrophage related cytokines (EGF, bFGF, IL-1 and IL-15) when compared with synovial fluid from patients with other early synovitis." (PMID 15987480, 2005).
systemic inflammatory response syndrome (1 paper, 2025). SIRS is a serious condition related to systemic inflammation, organ dysfunction, and organ failure. "Elevated IL-15 levels have been associated with more severe systemic inflammatory response syndrome and organ dysfunction, particularly renal and pulmonary dysfunction, in noncardiac surgical settings." (PMID 40854943, 2025).
systemic sclerosis (1 paper, 2007). A chronic disorder, possibly autoimmune, marked by excessive production of collagen which results in hardening and thickening of body tissues. "Several IL-15 signalling pathways are also implied in the putative pathogenesis of systemic sclerosis (SSc)." (PMID 17784951, 2007).
teratocarcinoma (1 paper, 2020). A germ cell tumor characterized by the presence of an embryonal carcinoma component and a teratoma component. "NeoTM-L19 is not glycosylated and we were pleased to see how the L19-based targeted delivery of the engineered IL2 and IL15 mimic led to an improved therapeutic effect for the F9 teratocarcinoma model." (PMID 33216834, 2020).
teratoma (1 paper, 2019). A non-seminomatous germ cell tumor characterized by the presence of various tissues which correspond to the different germinal layers (endoderm, mesoderm, and ectoderm). "In addition, in the absence of recombinant human IL-15 to support the proliferation of NK in our mice, our results also suggest that the relatively low number of NK cells injected during the AT procedure was sufficient to prevent the growth of teratomas." (PMID 31787975, 2019).
thymic epithelial tumors (1 paper, 2021). "Finally, pembrolizumab with or without SC-C101 (a superagonist fusion protein of interleukin-15) is currently ongoing as a phase 1/Ib study for 96 patients with pretreated solid tumors, including thymic epithelial tumors (NCT04234113)." (PMID 33802298, 2021).
thyroid (1 paper, 2025). "Therefore, IL-6, IL-15, and TNF-α were selected as representative indicators in this study to explore the potential interplay among thyroid function, inflammatory state, and skeletal muscle metabolism." (PMID 41355999, 2025).
thyroid-associated ophthalmopathy (1 paper, 2025). "Moreover, the expression of IL-15 has been reported to be significantly associated with the pathogenesis and progression of thyroid-associated ophthalmopathy." (PMID 41355999, 2025).
trachoma (1 paper, 2008). "New risk factors for chronic scarring trachoma included IL-6 and IL-15 (r = 0.259 and 0.292, respectively, P<0.005 for both) with increased levels for concurrent C. trachomatis infections (r = 0.206, P<0.05, and r = 0.304, P<0.005, respectively)." (PMID 18628987, 2008). "Additionally, C. trachomatis infections appeared to effect the IL-2 family of cytokines with a significant association of elevated IL-2 concentrations with controls; elevated IL-15 was associated with trachoma." (PMID 18628987, 2008). "The involvement of T lymphocytes in the perifollicular area of conjunctival follicles suggests an active involvement of the IL-2 family of cytokines, IL-2, IL-2R, and IL-15, in trachoma." (PMID 18628987, 2008).
transient arthritis (1 paper, 2023). Arthritis that is not permanent. "We also found new biomarkers that correlated with reactogenicity, including transient arthritis (MCP-2, CXCL10, CXCL11, CX3CL1, MCSF, IL-15, OSM)." (PMID 38235127, 2023).
tuberculous pleurisy (1 paper, 2012). "Therefore, the PFMCs from tuberculous pleurisy patients have the ability to produce IL-4 and IL-15 when stimulated with M.tb." (PMID 23028695, 2012).
type 2 thrombocytopenia (1 paper, 2013). "In several cell lines, PaCS development follows cell differentiation/activation by trophic factors and cytokines, such as GM-CSF and IL-4 for DCs, IL-2 and IL-15 for NK cells, or thrombopoietin, IL-6 and IL-11 for megakaryocytes in type 2 thrombocytopenia." (PMID 24358206, 2013).
Ureteral obstruction (1 paper, 2021). Obstruction of the flow of urine through the ureter. "The present study sought to examine if IL-15 treatment ameliorates tubulo-interstitial fibrosis in a mouse model of unilateral ureteral obstruction (UUO) in which the pathological role of TGF-β is well established and to decipher cellular pathways involved." (PMID 34769128, 2021). "Since endogenous IL-15 expression decreased in nephrectomized human allografts evolving toward fibrosis and kidneys in the unilateral ureteral obstruction (UUO) model, we explored IL-15’s renoprotective role by pharmologically delivering IL-15 coupled or not with its soluble receptor IL-15Rα." (PMID 34769128, 2021). "We first compared IL-15 and IL-15Rα mRNA expression in obstructed kidneys (UUO-kidneys) and contralateral non-obstructed kidneys (CTL-kidneys) on day-8 post-ureteral obstruction." (PMID 34769128, 2021).
urinary tract tumors (1 paper, 2025). "In addition to PD-1/PD-L1 inhibitors, recent studies have also highlighted the importance of other immune checkpoints, such as CXCR3 and IL-15, in regulating the immune response to urinary tract tumors." (PMID 40066439, 2025).
viral pneumonia (1 paper, 2020). Inflammation of the lung parenchyma that is caused by a viral infection. "However, based on the predictive modeling, IL-15 and IL-18 in combination with the metabolome and microbiome data may be more useful for distinguishing bacterial vs viral pneumonias." (PMID 32770049, 2020).
tumor (1,358 papers, 1998 to 2026). "We generated trifunctional antibody-cytokine fusion proteins composed of a scFv antibody directed against the fibroblast activation protein (FAP) as a tumor associated model antigen, IL-15 fused to an IL-15Rα fragment (RD), and either IL-7 or IL-21." (PMID 40370435, 2025). "CCR7+ IL12‐p40+ cDCs have been shown to associate with CD8+ T cells in perivascular regions of the tumour where they trans‐present IL‐15 to CD8+ T cells and are suggested to be important for the efficacy of immune‐checkpoint blockade." (PMID 40745918, 2025). "elaborately designed a biomimetic nanovaccine capable of delivering cytokine, which consisted of membrane vesicles, obtained from genetically engineered DCs with IL‐15/IL‐15 receptor α expression, tumor‐associated antigenic and costimulatory molecules." (PMID 40600457, 2025). "IL-15 shows potential in enhancing NK cell-mediated anti-tumor activity, while IL-18 is associated with poor survival outcomes due to its role in increasing immunosuppressive NK cells and upregulating PD-1 expression." (PMID 41169398, 2025). "For instance, STING agonists were found to enhance the migration and cytotoxic capacity of mesothelin-targeted CAR-NK cells and IL-15 helps overcome the loss of NK cell metabolic fitness induced by tumor interactions." (PMID 40761786, 2025). "Separately, subcutaneous delivery of cationic liposomes containing an IL-15-encoding plasmid as an adjuvant, paired with an autologous whole-cell tumor vaccine, achieved substantial tumor growth suppression in mice without adverse effects." (PMID 41196843, 2025). "Increasing number of publications evidences that exogenous administration of IL-15 prevents loss of NK cell effector functions in tumor microenvironment." (PMID 40071076, 2025). "Stress signals such as hypoxia, DNA damage, and pro-inflammatory cytokines (e.g., IFN-γ and TNF-α) upregulate IL-15 expression in tumor-associated macrophages and dendritic cells." (PMID 40299429, 2025). "Among the novel OVs being developed, the encoding of specific cytokines to stimulate tumor immune responses is an important research direction, with IL-7, IL-12, IL-15, and others representing key candidates." (PMID 40001666, 2025). "A mixed analysis of the covariance model with OS as the covariate at each time point showed that anti-tumor cytokines IL-8 and IL-15 were significantly associated with OS during Cycle 1 of therapy." (PMID 39457004, 2024). "Taken together, these results show that IT administration of the long-acting MS~RLI/IL-15 conjugates caused moderate tumor reduction and high anti-metastatic effects." (PMID 39559362, 2024). "All forms have demonstrated efficacy in causing tumor regression in animal experiments, which provides strong rationale for advancing IL-15 superagonist through clinical trials." (PMID 38368374, 2024). "Upon engagement of tumor cells by exogenous IL-15, we detected the association of IL-15Rα with the IL-2/IL-15Rβ and IL-2Rγ chains." (PMID 38637902, 2024). "We also found that tumor cell IL-15Rα was associated with IL-15β and IL-15Rγ upon engaging with extracellular IL-15." (PMID 38637902, 2024). "Various cytokines, including IL-2, IL-12, IL-15, IL-18, and IL-21, have been implicated in significantly enhancing NK cell yield and cytotoxic effects against tumor cells." (PMID 39633491, 2024). "IL-15 administration prevented loss of function and improved tumor control, generating intratumoral NK cells with both tissue-residency characteristics and enhanced effector function." (PMID 38267402, 2024). "In the MB49 model, it was shown that intravesical treatment with anti-CD40 agonist antibodies caused reduced tumour burden, whereby the therapeutic effect was reduced by blockage of IL-15." (PMID 38630912, 2024). "IFN-I enhance NK cell responses through direct and indirect action via DCs, causing IL-15 to promote NK cell activation and tumor elimination." (PMID 38672681, 2024).
tumor (continued). "In our cohort, it was observed that higher pre-treatment levels of IL-2 and IL-15 were associated with more aggressive tumor behavior and worse outcomes: patients survived less and had lower PFS." (PMID 39199571, 2024). "This is encouraging since intratumor T cells are more important in IL-15 anti-tumor efficacy and peripheral NK cell activation is associated with IL-15 systemic toxicity." (PMID 38315680, 2024). "This is a key advantage over IL-2-based therapeutics and importantly, IL-15 has been reported to prevent the loss of NK cell effector functions within the tumour microenvironment." (PMID 38223411, 2024). "In another study, IL-15-armored CAR-T cells completely prevented tumor relapse in a xenograft model but were associated with severe liver toxicity and a GvHD score." (PMID 38090585, 2023). "Peripheral blood NK cells can be briefly activated with IL-12, IL-15 and IL-18 to induce differentiation into memory-like NK cells, associated with enhanced responses when simulated through tumor targets for weeks to months after pre-activation." (PMID 37207215, 2023). "In cancer patients, decreased IL-15 expression has been shown to correlate with a lower proliferation of B and T cells, a higher risk of tumor recurrence, and decreased patient survival." (PMID 37371081, 2023). "Based on our findings, we propose that the increase of IL-15 in plasma caused by treadmill exercise plays a vital role in mediating NK cell recognition and killing the tumor." (PMID 37585912, 2023). "The biNV-IL-15 treatment not only inhibited the tumor growth but also prevented lung and liver metastasis of the tumor in contrast to IL-15:IL-15Rα and IL-15:IL-15Rα+biNV, causing an extended survival time." (PMID 37875481, 2023). "The study indicated that regular endurance training can reduce cancer risk, which was related to increased IL-15 expression, activation of the immune killing effect of NK cells, and promotion of tumor cell apoptosis, which can ultimately control tumor growth." (PMID 37585912, 2023). "The applied chemoimmunotherapy caused the highest inhibition of tumor growth in the group receiving DC/IL-15/IL-15Rα/TAg + DC/IL-18/TAg at the level of 72.4%." (PMID 37545526, 2023). "This study systematically evaluated the characteristics of IL-15 in various aspects, including expression pattern, survival prognosis, genetic mutation, tumor immune microenvironment, ferroptosis/cuproptosis, and signaling pathway." (PMID 36467072, 2022). "A fusion protein of IL-15-IL-15Ra and anti-FAP caused superior targeted anti-tumor killing ability, providing a rationale for the development of antibody-IL-15-IL-15Ra fusion proteins for cancer immunotherapy in the future." (PMID 36167591, 2022). "We further exploited the possibilities of this PD-1+ 2D3 based T-cell assay, by evaluating the tumor antigen-presenting capacity of PD-L-disrupted IL-15 DCs loaded with mRNA encoding the full-length WT1 protein." (PMID 35250967, 2022). "The engineering MG transfected with recombinant adeno-associated virus serotype 2 containing IL-15 were intranasally administrated to promote the maturation and survival of NK cells by IL-15 to kill tumor cells." (PMID 36311702, 2022). "Then, it was found that the overexpression of IL-15 was significantly associated with tumor status in COAD, SKCM, and COADREAD." (PMID 36467072, 2022). "Enrichment for TGF-β and IL-2/IL-15 signaling pathway genes further underlined the similarities of CD49a+ Eomes+ cells to cytotoxic ILC1ls, which can exert potent anti-tumor functions." (PMID 36372017, 2022). "The use of VSV virus vector encoding IL-15 (VSV-IL-15) in the murine CT-26 tumour model led to the enhancement of anti-tumour T-cell responses and enhanced survival." (PMID 36140243, 2022). "Ultimately, by targeting the tumor-associated antigen Wilms’ tumor-1 (WT1), the tumor-antigen specificity was assessed by demonstrating a superior antigen-specific T cell stimulating capacity of PD-L-silenced IL-15 DCs." (PMID 35250967, 2022).
tumor (continued). "These phenotypical changes were also associated with enhanced IL-15-mediated cytotoxicity against different tumor cell lines and HIV-infected CD4 T cells." (PMID 35867565, 2022). "Despite the small effect on tumor growth caused by IL-15 Gen or low dose (2.5 μg) of cyto-IL-15, only cyto-IL-15 in doses higher/equal to 5 μg had an effect on mice survival." (PMID 34778376, 2021). "In comparison to IL-2, T cell clones generated in the presence of IL-15 displayed higher proliferative capability and cytokine secretion potential and were effective in causing tumor regression upon transfer in mice." (PMID 33671252, 2021). "IL-15 has been described to cause an increased invasion of inflammatory cells to the tumor site and proliferation of adipocytes that consequently cause an increase in size." (PMID 32929618, 2021). "In brief, the shift from a Th1 to a Th2 inflammatory response will lead to an increase in immunosuppressive cytokine release (IL-2, IL-4, IL-7, IL-13, and IL-15) by neoplastic elements and tumor-associated cells, sustaining tumor growth and spread." (PMID 34685762, 2021). "It has been reported that IL-15 protects antigen-activated NKTs from suppression by tumor-conditioned hypoxic tumor-associated macrophages." (PMID 33668573, 2021). "While IL-15 alone has a short half-life, administration of IL-15 linked to soluble IL-15Rα significantly increases its half-life, leading to improved in vivo tumor response through increased survival of memory T and NK cells." (PMID 33410096, 2021). "TriKEs are composed of three separate binding regions including a single domain antibody (VHH) that binds CD16, an scFv that binds a tumor antigen present on cancer cells, and cross-linked wildtype human IL-15 that mediates cytokine signaling on the NK cells." (PMID 34439149, 2021). "There is evidence that decreased muscle mass causes reduced expression and the liberation of IL-6 and IL-15, which play a significant role in the redistribution and infiltration of natural killer cells involved in tumor cells elimination." (PMID 34684550, 2021). "By contrast, we find attractive interactions between NK cells and an IL-15-secreting variant of K562 tumor cells." (PMID 34294808, 2021). "For instance, IL-2, IL-15, and IL-21 are reported to promote tumor suppression in melanoma, whereas IL-1, IL-4, and IL-6 are associated with tumor progression in breast, prostate, and lung cancer." (PMID 33800170, 2021). "Here, IL‐15 caused a significant increase in the number of CD103+ DCs in the tumor while this was significantly lower in the groups following treatment with CD40 agonist." (PMID 32821382, 2020). "While the functional effect of Cish-deficiency in NK cells was obvious by their increased anti-tumor immunity and hyper-proliferative response to IL-15, it remained unclear how CIS regulated NK cell biology in vivo during steady-state." (PMID 32082327, 2020). "Administration of exogenous IL-15/IL-15Rα to Tyk2-deficient mice restores NK-cell maturation and NK cell-dependent control of tumor growth." (PMID 31936322, 2020). "A follow up study demonstrated that MeVac FmIL-12 was more effective at controlling tumors than MeV encoding IL-15 in two murine tumor models." (PMID 33178203, 2020). "While the functional effect of Cish-deficiency in NK cells was obvious by their increased anti-tumor immunity and hyper-proliferative response to IL-15, it remained unclear how CIS regulates NK cell biology in steady-state." (PMID 32082327, 2020). "MeVac variants encoding a murine version of the IL-15/IL-15Rα fusion protein (FmIL-15) were cloned and their immunomodulatory and anti-tumor activity was compared to MeVac FmIL-12 in two immunocompetent mouse models of measles oncolysis." (PMID 31623390, 2019). "Here, we demonstrated that F1 leads to NK cell activation via IL-15 upregulation, associated with increased granzyme B and perforin production to eliminate tumor cells, as well as higher levels of the antitumor IFNγ cytokine." (PMID 30717773, 2019).